MKI67 (marker of proliferation Ki-67)
Description:
Protein that associates with the surface of mitotic chromosomes and acts both as a chromosome repellent during early mitosis and chromosome attractant during late mitosis. Required to maintain individual mitotic chromosomes dispersed in the cytoplasm following nuclear envelope disassembly. During early mitosis, relocalizes from nucleoli to the chromosome surface where it forms extended brush structures that cover a substantial fraction of the chromosome surface. The MKI67 brush structure prevents chromosomes from collapsing into a single chromatin mass by forming a steric and electrostatic charge barrier: the protein has a high net electrical charge and acts as a surfactant, dispersing chromosomes and enabling independent chromosome motility. During mitotic anaphase, the MKI67 brush structure collapses and MKI67 switches from a chromosome repellent to a chromosome attractant to promote chromosome clustering and facilitate the exclusion of large cytoplasmic particles from the future nuclear space. Mechanistically, dephosphorylation during mitotic exit and simultaneous exposure of a conserved basic patch induce the RNA-dependent formation of a liquid-like condensed phase on the chromosome surface, promoting coalescence of neighboring chromosome surfaces and clustering of chromosomes. Binds premature ribosomal RNAs during anaphase; promoting liquid-liquid phase separation. Binds DNA, with a preference for supercoiled DNA and AT-rich DNA. Does not contribute to the internal structure of mitotic chromosomes (By similarity). May play a role in chromatin organization; it is however unclear whether it plays a direct role in chromatin organization or whether it is an indirect consequence of its function in mitotic chromosome.
Synonyms: MIB-1; PPP1R105; Ki-67; KIA; MIB-
Tractability: PROTAC: UniProt records ubiquitination sites on it; ubiquitination databases record sites on it.
Gene: Protein-coding gene on chromosome 10 (128,096,659 to 128,126,448, reverse strand). Ensembl gene ENSG00000148773.
Subcellular location: Chromosome; Nucleus; Nucleus, nucleolus
Subcellular location (Human Protein Atlas): Nucleoli rim; Mitotic chromosome; Nucleoplasm
Gene Ontology:
Molecular function: molecular condensate scaffold activity; protein binding; RNA binding
Biological process: chromosome segregation; regulation of mitotic nuclear division; cell population proliferation; meiotic cell cycle; regulation of chromatin organization
Cellular component: chromosome; condensed chromosome; membrane; nucleolus; nucleoplasm; nucleus
Genetic constraint (gnomAD): Loss-of-function variants: 145 observed, 231.49 expected, observed/expected ratio (o/e) 0.63, 90% interval 0.55 to 0.72. The upper end of that interval is the gene's LOEUF score, 0.72, which puts it in group 2 of 6, group 1 being the genes least tolerant of losing a copy. Missense variants: 3,837 observed, 3,937.7 expected, observed/expected ratio (o/e) 0.97, 90% interval 0.95 to 1. Synonymous variants: 1,430 observed, 1,434.9 expected, observed/expected ratio (o/e) 1, 90% interval 0.95 to 1.04.
Homologues: Orthologues: chimpanzee MKI67 (98% identical), macaque MKI67 (90% identical), dog MKI67 (45% identical), rat Mki67 (42% identical), mouse Mki67 (41% identical), zebrafish mki67 (13% identical), tropical clawed frog mki67 (12% identical). Paralogues in human: CDCA2 (5% identical).
Diseases named in the same sentence as MKI67 in open-access papers:
MKI67 is named in the same sentence as 1,112 diseases in open-access papers, as found by Europe PMC text mining. Sharing a sentence is not in itself a finding about the gene and the disease. The quoted sentences say what the papers report.
breast cancer (2,877 papers, 1988 to 2026). A primary or metastatic malignant neoplasm involving the breast. "We found that the expression of MKI67 (encodes Ki-67) is significantly correlated with the R2 signature in tumor cells (P = 2.4E-4, breast cancer; P < 2.2E-16, lung and gastric cancer), implicating the R2 signature in tumor progression." (PMID 35794212, 2022). "We found that both DNA repair and MKi67 expression were higher in high vs. low BRCAness group in BRCA1 mutation breast cancer in the TCGA cohort." (PMID 36371386, 2022). "It has been reported that Ki67 encoded by MKI67 plays an important role in the prognosis and treatment of breast cancer." (PMID 34322487, 2021). "For instance, lymphovascular invasion in breast cancer is associated with a higher-grade cell proliferation MKI67 expression, and an advanced stage; however, it is associated with survival only in early-stage disease." (PMID 33477315, 2021). "Mki67 (Ki67) is a widely recognized marker for cell proliferation and is associated with breast cancer prognosis statistically." (PMID 28212608, 2017). "IKWG Consensus Meeting reports that MKI67 level at 5% or less was significantly associated with good prognosis, while MKI67 level at 30% or more was significantly related to poorer prognosis in ER-positive early-stage breast cancer." (PMID 40070823, 2025). "MKI67 expression is correlated with outcome, and high MKI67 expression is associated with poor prognosis, which has been validated in a meta-analysis involving over 64 thousand breast cancer patients." (PMID 34408238, 2021). "Quantitative analysis of transcript abundance among the three sub-populations of OR genes confirmed that the genes associated with breast cancer cell proliferation (MKI67, AURKA, BIRC5, CCNB1, MYBL2) were significantly abundant in sub-population I with OR2B6 upregulation." (PMID 31551495, 2019). "Median gene expression of MKI67, encoding the proliferation marker Ki-67, was >10-fold higher in breast cancer samples than in adjacent controls, indicating that enhanced intron retention in normal breast is unlikely to be explained by contamination of adjacent control tissue by cancerous cells." (PMID 26113877, 2015). "Pathway enrichment revealed associations with cell cycle regulation (E2F3, MKI67), DNA repair (BRCA2), and transcriptional control (MED1), with six priority genes (MED1, BRCA2, E2F3, PITPNB, H1-1, and FARP2) showing established breast cancer relevance." (PMID 41614924, 2026). "Tumor cell proliferation rate, often assessed via MKI67 (Ki-67) IHC, is a well-established adverse prognostic feature for many tumor types such as breast cancer and gastrointestinal neuroendocrine tumors." (PMID 41201451, 2026). "MCM2 and MCM3 were more sensitive, specific and efficient proliferation markers for CRC and breast cancer than the Marker of Proliferation Ki-67 (MKI67)." (PMID 40998798, 2025). "Research further indicates that Ki-67 (MKI67), as a vital prognostic marker, has been extensively applied in the identification of various cancers, including breast cancer, gastric cancer, cervical cancer, and lung cancer." (PMID 39936154, 2024). "Accordingly, our results implicated that PNP, as well as PPP/NPP cells, are subsets of MKI67+ proliferative cells crucial for oestrogen‐dependent breast cancer growth, which correlated with the results from our ST analyses." (PMID 38282415, 2024). "To test this, we targeted the mRNA product of the MKI67 gene in a tissue microarray and imaged an entire section of a breast carcinoma tissue core on a widefield microscope." (PMID 38844629, 2024). "In line with the reported association with Ki67 (MKI67), TFRC correlated with a set of genes associated with highest proliferation in breast cancer." (PMID 38117806, 2023).
breast cancer (continued). "We found that the cellular landscape of MPEs was similar to primary breast cancer with respect to the presence of infiltrating lymphocyte and myeloid populations, and even recapitulated a distinct MKI67‐positive proliferative subpopulation." (PMID 37691350, 2023). "Mutations affecting the marker of proliferation Ki-67 gene (MKI67), encoding the Ki-67 protein, have also been identified in canine mammary tumors, but at a much lower rate (6% of cases)." (PMID 37835752, 2023). "According to our results, both of PSS and PL-treated BC cell lines contributed to a decrease of MKI67 expression implying that our extracts have a potential to suppress breast cancer cell proliferation through cell cycle arrest." (PMID 37264344, 2023). "Further investigations into breast cancer have previously yielded fundamental marker discoveries including Mki67+ as a prognostic marker, Cd44+/Cd24+ as a breast cancer stem cell marker, and Trop2 as another therapeutic target." (PMID 36630696, 2022). "The second study reported high inter-site and intra-site reproducibility of ESR1, PGR, ERBB2, and MKi67 mRNA measurements with the MammaTyper® test and showed a precise and reproducible assessment of the four breast cancer biomarkers." (PMID 34371382, 2021). "MKI67 has been regarded as a contributing component for molecular heterogeneity of breast cancer validated by previous studies." (PMID 34124255, 2021). "The four-gene score correlation in pancreatic cancer was higher than in breast cancer cohorts, specifically in the clinical aggressive parameters, which included pathological grade and MKI67 expression." (PMID 33291601, 2020). "A promising IHC biomarker for breast cancer is MKi67 (or Ki67), a protein that is indicative of cell proliferation and it is found in all active phases of the mitotic cell cycle." (PMID 33375043, 2020). "To investigate the clinical correlation among TROJAN, CDK2 and the proliferation marker MKI67, we performed qRT-PCR to measure their expression in ER+ breast cancer specimens." (PMID 32393270, 2020). "As an example, the following code filters the datasets for MKI67 (Ki67), breast tissue, and breast cancer." (PMID 31500569, 2019). "Use of an automated diagnostic platform (GeneXpert®) and assay (Xpert® Breast Cancer STRAT4) that employs RT-qPCR to quantitate ESR1, PGR, ERBB2, and MKi67 mRNAs from formalin-fixed, paraffin-embedded (FFPE) tissues facilitates analyses in less than 3 h." (PMID 30120700, 2018). "Based on these thresholds, the assay can be used for the robust quantification of ERBB2, ESR1, PGR and MKI67 on whole sections of FFPE samples during routine histopathological work-up of breast carcinoma." (PMID 30342538, 2018). "Nine genes in this module – Akt1, Brca2, Ccnd1, Dnmt1, Mki67, Palb2, Rrm1, Timeless, and Top2a – are known human breast cancer genes according to the MalaCards database; four of them are hub genes." (PMID 28212608, 2017). "From a technical perspective applying RT-qPCR for resolving the status of ERBB2, ESR1, PGR, and MKI67 represents an efficient and reproducible alternative for decentralized routine assessment of breast cancer molecular subtypes." (PMID 27389414, 2016). "In primary breast cancer, for instance, high MKI67 mRNA expression measured by RT-qPCR is predictive for achieving pathological complete remission (pCR) to neoadjuvant chemotherapy." (PMID 27610130, 2016). "A 5-gene assay was also developed quantifying the expression of CHDH, HOXB13, IL17BR, MIB1 and MKI67 to identify a subgroup of early stage estrogen receptor–positive breast cancer patients with very poor outcome despite endocrine therapy." (PMID 23468873, 2013). "Women carrying APOB non-GG and MKI67 non-AA genotypes exhibited the lowest breast cancer risk at the highest Pb levels (Q4), whereas carriers of APOB GG and MKI67 AA showed the lowest risk at the lowest Pb levels (Q1)." (PMID 41828541, 2026).
breast cancer (continued). "High tumor proliferation rate has been associated with aggressive tumor behavior in many malignancies, and MKI67 IHC is used in the clinical setting in breast cancer prognostic classification and gastroenteropancreatic neuroendocrine tumor classification, among others." (PMID 41201451, 2026). "Notably, when accounting for expression of ER (ESR1), HER2 (ERBB2), and Ki-67 (MKI67), PAFAH1B1 remained associated with worse survival from breast cancer." (PMID 40378956, 2025). "PILRA, MKI67, and UBE2C, as potential diagnostic and prognostic biomarkers, are anticipated to serve as promising therapeutic targets for the clinical management of both breast cancer and thyroid cancer." (PMID 41328437, 2025). "MKI67 is considered an important biomarker for classifying breast cancer." (PMID 37759508, 2023). "Next, we compared the distribution of high and low BRCAness score with DNA repair score and MKi67 expression with or without BRCA1-mutation in breast cancer." (PMID 36371386, 2022). "Further analysis demonstrated that the expression of cell cycle-related genes (CDC6, CDC25A, CDK1, ATM, E2F1, and MKI67) were much higher in breast cancer patients of 3 target genes high expression group or MIR3613 deletion group compared with their counterpart, respectively." (PMID 33494814, 2021). "These PCNA+ proliferating TAMs in breast cancer also had high expression of MKI67." (PMID 33144684, 2021). "Although Ki-67 protein levels have been proposed as a proliferation marker for discriminating luminal A and luminal B subtypes, no recurrent MKI67 mutations have been reported in human breast cancers." (PMID 32680987, 2020). "The gene MKI67 is often used as a surrogate biomarker to score the aggressiveness of the tumor, and expression of this gene has been used as a predictor of response to chemotherapy in breast cancer patients." (PMID 30991985, 2019). "Given the importance of MKI67 in separating Luminal A-like from Luminal B-like tumors, our study lends further support to the clinical significance of tumor proliferation and particularly MKI67 gene expression for the management of breast cancer." (PMID 31307414, 2019). "We did not observe a correlation between the three prognostic groups and mutations of PIK3CA, which is the most frequently mutated oncogene in breast cancer (P = 0.96), as well as mRNA level of the MKI67 gene, which encodes for the proliferation-related Ki-67 antigen (P = 0.073)." (PMID 29996935, 2018). "Moreover, the simple subtype showing the highest correlation in TNBC expressed KRT5 and MKI67, which has been known and used as immunohistochemical markers for basal-like breast cancer and proliferation." (PMID 30205506, 2018). "MKI67 is one of the genes near rs4590782 and has been studied extensively in breast cancer." (PMID 28120872, 2017). "Accurate determination of the predictive markers human epidermal growth factor receptor 2 (HER2/ERBB2), estrogen receptor (ER/ESR1), progesterone receptor (PgR/PGR), and marker of proliferation Ki67 (MKI67) is indispensable for therapeutic decision making in early breast cancer." (PMID 28490348, 2017). "Ten international pathology institutions participated in this study and determined messenger RNA expression levels of ERBB2, ESR1, PGR, and MKI67 in both centrally and locally extracted RNA from formalin-fixed, paraffin-embedded breast cancer specimens with the MammaTyper® test." (PMID 28490348, 2017). "Similarly, other investigators have also shown that FOXQ1 played a key role in nasopharyngeal carcinoma, targeted by miR-506 and miR-124; likewise, HMGB3 in breast cancer is targeted by miR-205; and MKI67 in hepatocellular carcinoma, targeted by miR-519d." (PMID 27119506, 2016). "Ki67, also known as MKI67, a nuclear protein associated with cellular proliferation, is a well-established marker for predicting the outcomes of patients with luminal breast cancer." (PMID 25073969, 2014).
breast cancer (continued). "Similarly, we chose RHOA, MKI67, CITED2, ACTA2, FN1 and TGFB3, as all have been implicated in EMT and highly metastatic breast cancer." (PMID 23441166, 2013). "Therefore, to link the expression pattern of the canonical luminal breast cancer markers with the ‘proliferative’ ST_2‐associated SC clusters, we further investigated our scRNA‐seq datasets using the classification based on ESR1/PGR/MKI67 expressions." (PMID 38282415, 2024). "The expression of key markers associated with proliferation (MKI67, PCNA, CCNB1, MYBL2, BUB1, CCND1), apoptosis (BCL2, CASP7, CASP8, CASP9, CASP3, BAX, APAF1), differentiation (CDH1, CD24, EPCAM, ESR1, NGFR, RUNX1), and breast cancer stemness (CD44, ITGA6, DNER, ALDH1A3, ABCG2, PROCR) was assessed." (PMID 35183258, 2022). "Expression of mRNA for COX2, P16/INK4A, and KI67 (encoded by PTGS2, CDKN2A, MKI67, respectively) and estrogen receptor beta (ERβ, encoded by ESR2) were analyzed because prior studies suggested these as biomarkers of AH at greater risk of progression to breast cancer." (PMID 31248446, 2019). "Comparing the prognostic value of FGD3 in breast cancer with the prognostic value of genes associated with proliferation such as MKI67, PCNA, and AURKA indicates that FGD3 may offer superior disease progression metrics in all clinically relevant breast cancer subtypes." (PMID 32913979, 2017). "In this study we show that the 11-gene proliferation score and the individual proliferation marker MKI67 can be successfully predicted using a CNN model and routine H&E stained breast cancer histopathology slides." (PMID 39663527, 2024). "The metastasis-related gene MMP11 and proliferation-related genes BIRC5, MYBL2, MKI67 (Ki67), AURKA (STK15), CCNB1, and ERBB2 (HER2) from the Oncotype DX gene set exhibit significant up-regulation in tumor samples of breast cancer (BRCA)." (PMID 38254834, 2024). "Subsequently, we performed univariate and multivariate Cox regression analyses on the relationships among KNSTRN, HER2 (ERBB2), ER (ESR1), and Ki67 (MKI67) expression, clinical factors (age, race, and pTNM-stage), and OS in patients with breast cancer." (PMID 38198023, 2024). "In our results, heterogeneous distribution of the expression of breast cancer-related genes (ESR1, PGR, ERBB2, and MKI67) was observed." (PMID 37759508, 2023). "We previously identified mRNA-based methods involving PCR blood tests for five markers (EPCAM, KRT19, ERBB2, MKI67, and TERT) as an alternative breast cancer screening tool." (PMID 36012405, 2022). "The Xpert® Breast Cancer STRAT4* Assay (STRAT4)*, a standardized test for ESR1/PGR/MKi67/ERBB2 mRNA biomarker assessment, takes less than 2 hours." (PMID 33879115, 2021). "Taken together, Xpert® Breast Cancer STRAT4 mRNA testing for ESR1, PGR, ERBB2, and MKI67 demonstrated good performance when compared to the diagnostic gold standard IHC/ISH." (PMID 34572945, 2021). "The input features are the corresponding genes of well-established breast cancer biomarkers (ESR1, PGR, ERBB2, MKI67, PLAU) and the hybrid ensemble approach's final selected genes." (PMID 34290286, 2021). "Breast cancer clinical treatment selection is based on the immunohistochemical determination of four protein biomarkers: ESR1, PGR, HER2, and MKI67." (PMID 34408238, 2021). "Genes related to proliferation (MKI67, CCNA2), differentiation (EPCAM, CDH1), epithelial to mesenchymal transition (VIM, SNAI2), pluripotency and breast cancer stem cells (SOX2, NANOG, CD44) were included." (PMID 34090457, 2021). "A point-of-care mRNA STRAT4 breast cancer assay for ESR1, PGR, ERBB2, and MKi67, for use on the GeneXpert platform, has been recently validated on tissues from internationally accredited laboratories, showing excellent concordance with IHC." (PMID 34050358, 2021). "Public TCGA data showed that MKI67, the marker of cell proliferation 15, had a significant positive correlation with CHK1 (R2 = 0.46, P = 1.19e-162) in breast cancer." (PMID 32210727, 2020).